ERBB2 (erb-b2 receptor tyrosine kinase 2)
Diseases named in the same sentence as ERBB2 in open-access papers (continued):
Sharing a sentence is not in itself a finding about the gene and the disease.
cancer (continued). "As previous report, our data showed that MB sequencing also detected PIK3CA, ERBB2 and KRAS subclonal mutations, which are linked to therapy response in various cancers." (PMID 32099048, 2020). "Another Tier 1 gene identified by NIMBus, ERBB2, is a transmembrane tyrosine kinase receptor that is often overexpressed in cancer." (PMID 33092526, 2020). "This has been associated with the development of longer, more toxic, and more costly multidrug regimens for ERBB2-positive cancers." (PMID 33226431, 2020). "Another mucin, mucin 13 (MUC13), promotes the progression of various cancer types, including CC, through induction of ERBB2 expression and NF-κB activation." (PMID 32708604, 2020). "The ERBB family of tyrosine kinase receptors, including EGFR (ERBB1/HER1), ERBB2 (Neu/HER2), ERBB3 (HER3), and ERBB4 (or HER4), has largely been associated with cancer pathogenesis and epithelium-mesenchymal transition (EMT)." (PMID 32316671, 2020). "The third molecular subtype, HER2-positive cancer, has a predominant expression of HER2/ERBB2 oncogene." (PMID 32521684, 2020). "ERBB2 is altered by amplification and/or overexpression in various cancer types, and antibodies that bind to the extracellular domain of HER2 are now standard-of-care in ERBB2 amplified breast and esophagogastric cancers." (PMID 32332851, 2020). "A correlative microscopy method was established to analyze the spatial correlation of the functional state of ErbB2 with the abundance of actin in whole cancer cells." (PMID 32714928, 2020). "MZF1 seems to be a central regulator of invasion-associated pericellular lysosome distribution and lysosome-mediated invasion of ErbB2 expressing highly invasive cancer cells." (PMID 31963147, 2020). "ErbB2 plays a key role in cancer cell growth, and metastasis and, as such, resembles an important target for cancer treatment." (PMID 32714928, 2020). "Neuregulin-1β, an ErbB receptor (HER2) family ligand, has been proven effective against Doxorubicin-induced cardiotoxicity, but is also pro-neoplastic in many cancers via formation of ErbB2/3 interactions." (PMID 32322588, 2020). "In this study, we analyzed a large number of 10,000 patients with advanced cancers for oncogenic mutations in EGFR, ERBB2, BRAF, and MAP2K1, especially for those located within the kinase domain β3‐αC loop." (PMID 32757330, 2020). "This peptide-targeting strategy has the potential to improve the efficacy of chemotherapy in ErbB2-positive cancers." (PMID 32599712, 2020). "In this study, we applied correlative FM and STEM of graphene-covered whole cancer cells to investigate distribution patterns of membrane ErbB2 in spatial relation to actin." (PMID 32714928, 2020). "It should be noted that the current clinical indication for the approved ERBB2 inhibitors afatinib, lapatinib, and neratinib is limited to cancers with ERBB2 amplification and overexpression." (PMID 32366937, 2020). "One compelling approach is suggested to suppress ErbB2-positive cancer growth via promoting ErbB2 degradation." (PMID 32327714, 2020). "Various EGFR-and ERBB2-CAR-T clinical trials are also under evaluation for patients with various cancer types (ClinicalTrials.gov Identifier: NCT03618381, NCT03638167, NCT03696030, NCT03198052, etc.)." (PMID 32708604, 2020). "As a member of the epidermal growth factor (EGF) receptor family, ERBB2 overexpression and activation in cancer metastasis have been well recognized." (PMID 33042286, 2020).
cancer (continued). "In conclusion, based on a large cohort of cancer patients, our study analyzed mutations in β3‐αC loop in kinase domain of EGFR, ERBB2, MAP2K1, and BRAF, and summarized the drug‐relevant mutations of each gene." (PMID 32757330, 2020). "TGFβ signaling amplifies oncogenic ErbB2 signaling and promotes invasion and metastasis of ErbB2 positive cancer cells." (PMID 31963147, 2020). "Among these, open reading frames of at least 23 genes (23/42 = 55%), including cancer genes such as ERBB2, FOLH1 and ULK2, were predicted to be altered by these SMNTs and their combined structural variant events in the vicinity." (PMID 32024997, 2020). "In cancer cells, ERBB2 represents the preferred partner of other members of the ERBB receptor family, leading to stronger oncogenic signals, by promoting both ERK and AKT activation." (PMID 33037285, 2020). "In cancers that overexpress the product of the oncogene erbB2, therapy combines the use of anthracyclines with ErbB2-blocking antibodies (trastuzumab or herceptin)." (PMID 32655416, 2020). "Already in 1998, trastuzumab(Herceptin), a monoclonal antibody specific for cancer cells that produce excessive oncoprotein HER2 (human epidermal growth factor receptor 2, also known as ErbB2), was approved in the treatment of metastatic breast cancer." (PMID 33297561, 2020). "Overexpression of ErbB2 affects the actin cytoskeleton, and thus plays a role in the metastatic progression in cancer cells, which resembles the major cause of mortality." (PMID 32714928, 2020). "Patients who have hormone-receptor-positive tumors receive endocrine therapy, and those with ERBB2-positive cancer receive a monotherapy of an ERBB2-targeted antibody or in combination with chemotherapy." (PMID 33113766, 2020). "In order to determine the proportion of ERBB2-high tumors in other cancer types, we explored ERBB2 expression for 10,071 tumors of different origins." (PMID 32674482, 2020). "This work implied for the first-time involvement of lysosomes in the invasion of ErbB2-expressing cancer cells." (PMID 31963147, 2020). "A different strategy is the search and use of embryonic antigens, as A19, which was demonstrated to be an effective targeted agent for Erbb-2 expressing cancers." (PMID 32351900, 2020). "Our panel included cancer cell lines with activating PIK3CA mutations, inactivating PTEN mutations, AKT gene amplification or amplification of either ERBB2 or MET (both of which have been previously shown to be associated with AKT dependence)." (PMID 32439931, 2020). "Those complexes are associated with the DNA condensation during cell division and have transcriptional-based relationships with ERBB2 signaling pathway and cancer development." (PMID 33424936, 2020). "While Esr1 was about 2-fold downregulated and Pgr showed zero expression, Erbb2 had a comparable expression in 4T1 vs. the non-cancer mammary gland samples (about 20 TPM)." (PMID 32793490, 2020). "Once NF-kB is activated, it triggers the nuclear translocation of IKK in ERBB2-positive cancer cells." (PMID 33066388, 2020). "To further determine the relationship between NEAT1_2 and HER2 expression in the Oslo2 cohort, we investigated the correlation between NEAT1_2 levels and ERBB2 copy number and mRNA expression in HER2-positive and HER2-negative cancers." (PMID 31992741, 2020). "This previously unrecognized role of ERBB2 as a negative modulator of other ERBBs activity opens new perspectives for the treatment of ERBB2-positive carcinomas." (PMID 33037285, 2020). "VEGF is the central component of pathological blood vessel formation, and it was reported that EGFR and ERBB2 signaling pathway plays an essential role in VEGF regulation in carcinoma cells." (PMID 32224504, 2020).
cancer (continued). "It has been reported that combinatorial treatment of human cancers with anti-ErbB2 and anti-EGFR antibodies leads to more effective growth inhibition than either treatment alone." (PMID 31470510, 2019). "ERBB2 amplification was often mutually exclusive with other oncogenic alterations in gastric (83.3%; 5/6) and colorectal (60%; 3/5) cancer patients." (PMID 31019892, 2019). "Our findings in this study indicate that CLCN3 promotes 3D spheroid proliferation in ErbB2-overexpressing breast epithelial and cancer cells." (PMID 31608175, 2019). "Cooverexpression of Grb7 and ERBB2 are strongly associated with a worse prognosis than that of ERBB2 overexpression alone, suggesting the clinical significance of both Grb7 and ERBB2 genes/proteins expression in cancer development." (PMID 31083325, 2019). "The new method enabled to measure distinct levels of ERBB2 gene expression in cancer cell lines and patient-derived DCCs and allows addressing specific research questions with little resources." (PMID 31430289, 2019). "In this study, we analyzed Lapatinib sensitivity to EGFR and ERBB2 targeted therapy pan-cancer cell line wide." (PMID 30842786, 2019). "In this work, the cancer biomarker ERBB2 and the TOP2α gene showed to be correlated at its copy number." (PMID 31301170, 2019). "The human epidermal growth factor tyrosine kinase receptor (EGFR/ERBB) family, which includes four members: HER1 (EGFR, ErbB1), HER2 (Neu, ErbB2), HER3 (ErbB3), and HER4 (ErbB4) have been associated with many human cancers." (PMID 31470531, 2019). "In ERBB2 positive cancer cells, knockdown of Grb7 has been found to decrease integrin-mediated RAC1 activation as well as integrin-mediated cell movement." (PMID 31083325, 2019). "The positive rates of HER2/c-erbB-2 in the cancer and paired normal gastric tissues were 32.8% (22/67) and 4.5% (3/67), respectively with statistical difference (p<0.05)." (PMID 33817143, 2019). "Most recently, our work on membrane protein communities and cancer membrane protein-regulated networks discovered 13 new interaction proteins (e.g., ERBB2) with α9-nAChR across human cancers." (PMID 31505803, 2019). "The positive expression rate of HER2/c-erbB-2 in the cancer and paired normal gastric tissues were 32.8% (22/67) and 4.5% (3/67), respectively with statistical difference (p<0.05)." (PMID 33817143, 2019). "The majority of ERBB2 copy number gains across cancer types, however, were in fact focal; accounting for 85 and 71% of calls in GI and non-GI cancers, respectively." (PMID 31019892, 2019). "Trastuzumab (Herceptin) is a humanized anti-HER2 monoclonal antibody used in aggressive cancers with overexpression of human epidermal growth factor receptor 2 (HER2/ERbB2)." (PMID 32309607, 2019). "Taken together, ERBB2 is required for the dysregulation of cancer-related genes, such as MED24, during lung tumor development." (PMID 31248101, 2019). "Here we exploited the transplantable primary NeuT cell model, NeuT-TUBO and p140-TUBO cells, to capture the p140Cap molecular complexes and to pinpoint interactions crucial for regulation of ERBB2-positive cancer-specific features." (PMID 31681758, 2019). "ERBB2 amplification was most frequently identified in gastric (21.4%; 6/28), colorectal (11.1%; 5/45), lung (3.9%; 9/231), and breast (3.2%; 1/31) cancer patients." (PMID 31019892, 2019).
cancer (continued). "IKKα is necessary for ERBB2-induced breast tumorigenesis and plays an essential role in self-renewal of cancer stem cells." (PMID 31796128, 2019). "For example, mutations in EGFR and amplification of ErbB2 predict sensitivity to EGFR and ErbB2 targeting cancer drugs, respectively." (PMID 31536605, 2019). "The erbB2 expression was detected to be increased in 20–30% of human BCs ErbB2 (HER2) positive BC strongly related to poor prognosis that result in emerging metastases nature of cancer and intrinsic resistance to endocrine and routine chemotherapy." (PMID 30975222, 2019). "The studies also show that the cytotoxic activity of lapatinib on the cancer cell lines is due to the overexpression of ErbB1 and/or ErbB2 or varying levels of both ErbB1 and ErbB2 expression." (PMID 31905843, 2019). "As previously reported, combinatorial antibody treatments against different targets induce synergistic effects; in particular, several clinical studies combining PD-L1/PD-L1 inhibitors with either ErbB2 or EGFR-TKIs in cancer patients are on-going." (PMID 31470510, 2019). "Presumably, amplification of the gene ERBB2 is a biological indication of a more aggressive cancer phenotype; it has been shown that HER2 overexpression, due to amplification of this gene, in GC is associated with worse prognosis." (PMID 31645889, 2019). "Treatment with lovastatin (inhibitor of cholesterol biosynthesis, alternative to simvastatin) improved the therapeutic potential of anti-cancer drugs targeting ErbB2, lapatinib or neratinib." (PMID 31878945, 2019). "The copy number and expression levels of both GRB7 and ERBB2 are highly increased in many human cancers." (PMID 31083325, 2019). "Nevertheless, liposomes containing cytotoxic drugs and targeted via anti-HER2 (ErbB2) monoclonal antibody fragments have been utilized in cancer chemotherapy." (PMID 31159417, 2019). "On 4T1 cells, siRNAs against AKT and ERBB2 plus paclitaxel or docetaxel resulted in the largest increase in anti-cancer effects compared to CA/paclitaxel or CA/docetaxel." (PMID 31484456, 2019). "Ingenuity Pathway Analysis (IPA) of these genes impacted by Erbb2 ablation in the cancer model showed that they are significantly related to cancer, cellular movement, cell death, and survival." (PMID 31248101, 2019). "Here we demonstrate, for the first time, that high level, focal ERBB2 gene amplification, as identified by cfDNA testing, is a common event in Asian patients with advanced cancers." (PMID 31019892, 2019). "A19 was elucidated to internalize into cancer cells following binding to Erbb-2 and hence developed as an antibody-drug conjugate (ADC)." (PMID 30072783, 2018). "Seventeen percent of BRCA and UCEC express PGR and 9.4% of BRCA express ERBB2 in our cohort, reflecting the FDA-approved use of anti-estrogen hormone therapy and HER-2 inhibitors, respectively, in these cancer types." (PMID 30053901, 2018). "In further microarray studies of other EGFR and ErbB2-driven cancer cells, a largely overlapping group of genes was consistently noted to be regulated." (PMID 29861842, 2018). "This strategy was then used to target cancer cells via an antibody against the well-known cancer marker HER2/neu (AKA ERBB2)." (PMID 29904022, 2018). "To ensure that these effects are specific only to cancer cells, we tested the effect of lapatinib on normal mammary epithelial cells (MECs) isolated from H/H;ERBB2 mice." (PMID 29799521, 2018). "MYC, CDK6, PRKACA, and ERBB2 genes were found to frequently interact with other cancer-related genes." (PMID 29716549, 2018). "The results obtained with GroA prompted us to examine its effect in combination with ErbB2 inhibition on cancer cell growth, in an attempt to improve treatment outcome." (PMID 29352243, 2018). "To understand the specific interactions between ganetespib/HSP90 and ErbB2, we particularly examined the effects of ganetespib on ErbB2 protein stability and its effects on cancer cells with different ErbB2 statuses." (PMID 29717218, 2018).
cancer (continued). "Several genes account for a large proportion of variant/drug interactions (e.g., EGFR, KIT, ERBB2, BRCA1, PDGFRA), reflecting interest in therapeutically exploiting a relatively limited number of cancer driver genes." (PMID 30053901, 2018). "The combination of ErbB2-targeting therapeutics, like lapatinib, with other anti-cancer agents has been used as therapeutic strategy in the clinic to increase drug potency and improve patient responses." (PMID 29717218, 2018). "Recognized cancer-related kinases are again observed in this set, including ERBB2, FGFR2, PTK6, RAF1 and RON (MST1R) as well as 22 understudied kinases." (PMID 29643987, 2018). "Later on, the use of trastuzumab in cancer patients has highlighted the protective role of the ErbB2 signaling also on the adult heart; this signaling is essential for survival, growth, and apoptosis inhibition of cardiomyocytes." (PMID 29743983, 2018). "Our results demonstrated that ErbB2-overexpressing cancer cells (MDA-MB-435/ErbB2 and MCF7/ErbB2) were more sensitive to ganetespib than the parental cells (MDA-MB-435/Control and MCF7/Control), as indicated by both MTT and clonogenic assays." (PMID 29717218, 2018). "Remarkably, we found this type of mutation in BRAF, ERBB2, JAK2, and EGFR in cancer genomes, suggesting that the dimerization works as a principal mechanism to regulate the activity of these kinases." (PMID 29930381, 2018). "Lastly, we demonstrate that PHLDA2 expression has functional impact in EGFR/ErbB2-driven cancer cells and can modulate the efficacy of molecularly targeted therapy." (PMID 29861842, 2018). "To functionally test the ability of T cells to promote brain metastasis, we used a cancer cell line (ErbB2-P) established from a spontaneous ErbB2 + mammary tumor derived from MMTV driven-NeuNT transgenic mice." (PMID 29350274, 2018). "Here, we identify endogenous T cell responses in patients with cancer to 3 different recurrent oncogenic driver mutations: BRAF V600E, KRAS G12V and the ERBB2 (Her2) internal tandem duplication (Her2-ITD)." (PMID 30400835, 2018). "Better understanding of PHLDA2′s regulation and its interactions with membrane PIPs/inhibition of AKT activation can yield novel therapeutic options for the treatment of patients with EGFR/ErbB2-driven cancers." (PMID 29861842, 2018). "In several cancer cells overexpressing ErbB2, inhibition of ErbB2 alone by specific inhibitors seems to be impossible since it is well known that ErbB2 is the preferential partners of the ErbB receptors, including EGFR." (PMID 29662626, 2018). "Since we have also observed a concomitant decrease in nucleolin binding to ErbB2 both in vitro and in vivo, it is plausible to assume that the anti-cancer effects of GroA were mediated by the disruption of ErbB2–nucleolin complexes." (PMID 29352243, 2018). "Which patients with Erbb2-positive cancers will benefit from ErbB2-trageted therapies cannot currently be predicted." (PMID 30545388, 2018). "Mutations and overexpression of ERB receptors (ERBB2 and ERBB3 in this network) have been strongly associated with more than 10 types of tissue-specific cancers and they can be seen at the highest level regulating most of the acyclic network." (PMID 30225028, 2018). "Rare and possibly damaging variants were identified in 12 candidate genes in this cohort, including variants in DNA repair genes (ERCC1 and SXL4) and other cancer-related genes (NOTCH2, ERBB2, MST1R, and RAF1)." (PMID 29868112, 2018). "ErbB2-overexpressing cancer cells were also more sensitive to ganetespib-mediated growth inhibition than parental cells." (PMID 29717218, 2018). "Therapeutic agents targeting EGFR and ErbB2 are now currently used in treating a variety of cancers." (PMID 29348142, 2018).